IL4 (interleukin 4)
Diseases named in the same sentence as IL4 in open-access papers (continued):
Sharing a sentence is not in itself a finding about the gene and the disease.
leishmaniasis (46 papers, 2009 to 2025). Infectious disease that is transmitted through the bite of hematophagous female phlebotomine sand flies. "Under this study, 3 cytokines (IL-4, IL-6 and IL-10), with a role in increasing susceptibility towards leishmaniasis progression (Th2 response), were estimated in PBMC supernatants." (PMID 38918456, 2024). "Susceptibility to leishmaniasis has been extensively associated with anti-inflammatory cytokines, as demonstrated in IL-4, IL-6, IL-10 and IL-13 deficient BALB/c mice." (PMID 37691941, 2023). "The Th1 (IFN-γ) and Th2 (IL-4) cytokines, which induce classically-activated (M1) or alternatively-activated (M2) macrophages, underlie resistance versus susceptibility to leishmaniasis." (PMID 34249011, 2021). "The production of high levels of IL-18, along with high levels of IL-4 (Th2 biased response), has been associated with worse prognosis in other infections such as leishmaniasis." (PMID 33552997, 2020). "The “B-helper” follicular T-cell (Tfh) lineage is also implicated in leishmaniasis progression, which is the source for bulk production of IL-4 in the draining lymph nodes of susceptible mice infected by L. major." (PMID 31024534, 2019). "The production of cytokines in leishmaniasis plays a key role in maintaining susceptibility or resistance to disease, with cytokines IL-10, IL-4, TGF-β and IFN-γ being more relevant." (PMID 28848541, 2017). "Later on, they show a dramatic progression of disease, whereas IL-4-deficient mice are well protected; pointing to a protective role of IL-13 in leishmaniasis." (PMID 24475277, 2014). "Disease progression in the murine leishmaniasis model is also associated with IL-4 production and development of Th2 immune responses, whereas resistance is mediated by IFN-γ and Th1 cells." (PMID 24475277, 2014). "Protection against leishmaniasis is associated with a Th1 immune response characterized by high levels of IL-12 and low levels of IL-4." (PMID 22802978, 2012). "Although IL-4 has been accepted as inductor of susceptibility in leishmaniasis, some studies have shown its importance in the generation, proliferation and maintenance of memory cells in experimental infections by L. donovani and Plasmodium yoelii." (PMID 22463817, 2012). "Studies on murine model established the pathogenic role of IL-4 in leishmaniasis." (PMID 31024534, 2019). "IL-2 may act as a susceptibility factor in leishmaniasis by inducing the production of IL-4 from CD4+ T-cells." (PMID 31024534, 2019). "In addition, leishmaniasis pathogenesis is associated with the blockage of a Th1 response development, leading to a greater number of IL-4 and IL-10-producing cells in the lesions." (PMID 31024859, 2019). "In this study, two undernutrition infected groups showed more severe leishmaniasis, with increased parasite load in the spleen, upregulated expression of PD-1 and PD-L1, elevated serum IL-4 and IL-10, and decreased serum antibodies, TC and LDL-C." (PMID 38185681, 2024). "Genetic mapping studies conducted in murine models have identified a genomic region that encompasses the IL4 and IL13 genes as a susceptibility region for leishmaniasis." (PMID 37908348, 2023). "These cytokines were strategically quantified in the murine model of leishmaniasis because the IL-4 cytokine induces the polarization of the immune response to a Th2 immune pole, in which macrophages become permissive to parasite multiplication." (PMID 37242490, 2023). "Patients with recurrent leishmaniasis presented a positive correlation between the levels of IL-2, IL-4 and TNF (p<0.001)." (PMID 36017367, 2022). "While IL-4 blockade of protective responses can contribute to the uncontrolled Leishmania replication in experimental models, IL-4 appears to be less important in DCL patients or indeed in any form of human leishmaniasis." (PMID 33841444, 2021).
leishmaniasis (continued). "In the control group, the concentration of IL-4 increases after leishmaniasis that results in aggravation of the infection as discussed by Sacks and Trauth." (PMID 34094593, 2021). "It is well known that pro-inflammatory (e.g., IFN-γ, TNF-α, IL-1, IL-12) and anti-inflammatory (e.g., IL-4, IL-10, TGF-β) cytokines play different roles in resistance/susceptibility and the immunopathogenesis of leishmaniasis." (PMID 33114674, 2020). "The production of cytokines, such as IL-4, IFN-γ, and IL-10, plays a key role in the susceptibility or resistance to leishmaniasis." (PMID 32867857, 2020). "IL-4 cytokine is responsible for maturing B cells, which, in turn produce antibodies, that in leishmaniasis are ineffective, since parasites are hidden in the intracellular environment." (PMID 33092305, 2020). "IL-4 produced at these early timepoints then signals various immune cell populations to promote leishmaniasis." (PMID 32948646, 2020). "The important role of IL-4 in the generation of CD8+ T cell memory against leishmaniasis has been shown in previous studies." (PMID 28114333, 2017). "In experimental models of leishmaniasis, upregulation of PPARγ by IL-4 was demonstrated to instill monocytes/macrophages with potent anti-inflammatory and Th2 functionalities, essential for disease progression." (PMID 26496711, 2015). "It has been published for experimental leishmaniasis that IL-4 instructs dendritic cells to increase IL-12 production leading to development of Th1 immune responses." (PMID 24475277, 2014). "The expression level of IL-1β by epidermal keratinocytes is one of the decisive factors for generating protective Th1 immunity during experimental Leishmaniasis, along with IL-12, IL-4, IL-6, and osteopontin." (PMID 23286586, 2013). "Resistance in leishmaniasis has been reported to depend on DC-derived IL-12, the inhibition of Leishmania-specific IL-4-secretion by Vβ4Vα8 CD4+ T cells and the induction of a Th1-dominated immune response in vivo." (PMID 22802978, 2012). "The presence of IL-4 during T cell priming resulted in the development of Th2 cells, which even rendered resistant TCR Vβ4-deficient BALB/c mice susceptible to leishmaniasis." (PMID 22802978, 2012). "The Th1/Th2 paradigm of experimental leishmaniasis is associated with IL-12- and IFN-γ-mediated resistance or IL-4-mediated susceptibility to L. major infection." (PMID 22802978, 2012). "IL-4 acting on DC induced the generation of a protective Th1 immune response against leishmaniasis in BALB/c mice." (PMID 22802978, 2012). "Moreover, the overproduction of Th2 cytokines can result in chronic inflammation, as in leishmaniasis, where the activation of IL-4 and IL-13 results in pathogen expansion and chronic infection." (PMID 37569646, 2023). "These authors also observed an in vivo exacerbation of leishmaniasis lesions, and they associated with IL-10 induction, but not IL-4, to this immune response downregulation." (PMID 34276650, 2021). "For Leishmania amazonensis, one of the main etiological agents of leishmaniasis in the Amazonian region, a Th2 response against infection is generally developed, confirmed by the presence of high levels of IL-4 and IL-10, and accompanied by the production of IgG1 antibody isotypes." (PMID 34253188, 2021). "IL-4 is considered as a Th2 cell-related pathway in leishmaniasis." (PMID 34140933, 2021). "IL-4 quenches the activated macrophages and promotes Th2 responses in leishmaniasis." (PMID 30811391, 2019). "Hence, increased IFN-γ and IL-6 levels as well as decreased amount of IL-10 and IL-4 skewed to the healing process in leishmaniasis." (PMID 30811391, 2019). "It is reported in the literature that if IL-4 is presented in the earlier phase of leishmaniasis it leads to the production of IL-12 and prime Th1 cells, while if it is presented during Th-cells priming it will lead to Th2 production and will suppress the expression of the IL-12 receptor." (PMID 28775959, 2017).
leishmaniasis (continued). "Together, these findings suggest that IL-4 is a strong adjuvant to induce Th1-biased immunity against leishmaniasis and possibly other infections with intracellular pathogens, indicating that IL-4 needs to be considered in the development of efficient cell-mediated vaccination strategies." (PMID 22802978, 2012). "As yet, there is no information to suggest that IL-4 and IL-10 are engaged in downregulating the Th1-type immune response in human leishmaniasis caused by L. donovani; however, further study is needed to identify the role of Th2 cells in L. martiniquensis infection in both human and murine models." (PMID 34977224, 2021). "Test for a possible regulatory role of miR-194 in the production of cytokines IL-1β, IL-6, IL-4, TNF-α, IFN-y, TGF-β, and IL-10, PBMCs from healthy dogs and those with leishmaniasis were transfected with miR-194 Mimic and Inhibitor." (PMID 38241360, 2024). "We observed higher levels of IL-4 and TGF-β in the supernatants of PBMCs from dogs with leishmaniasis than from healthy dogs, confirming the regulatory role of these cytokines in CanL." (PMID 38241360, 2024). "Reciprocity of cytokines have been previously investigated for IFN-γ and IL4 where, IFN-γ regulated Th2 response and IL4 regulated Th1 response during Leishmaniasis in murine models at temporal levels." (PMID 35126456, 2021). "A set of cytokines and chemokines can influence the cellular immunity to leishmaniasis, comprising, but not limited to, IFN-γ, IL-4, IL-12, IL-13, TNF-α, and IL-10." (PMID 34140933, 2021). "Our studies show that IL-4 produced during the early timepoints following infection plays a central role in programming CD4+ and CD8+ T cell responses that promote leishmaniasis in BALB/c mice." (PMID 32948646, 2020). "In contrast, the acquired immune response observed in patients with leishmaniasis is related to a Th2 immune response with a high production of IL-4, IL-10, or TGF-β, cytokines that are not protective to the vertebrate host." (PMID 37242490, 2023). "So far, there is no information that IL-4 is engaged in downregulating the Th1 type immune response in human leishmaniasis." (PMID 33680991, 2021). "In subjects cured of leishmaniasis, IL-4 also did not inhibit lymphocyte proliferative response or IFN-γ production." (PMID 33680991, 2021). "The results show that complete protection against otherwise lethal leishmaniasis required immunization of BALB/c mice with IL-4-responsive BMDC, while IL-4Rα−/− BMDC failed to induce the restriction of lesion development." (PMID 22802978, 2012). "On the other hand, the level of IL-4 secretion by Lip-WLL was remarkably greater than other groups including Buffer, confirming that the co-existence of WLL and sphingomyelin liposome could elevate the signs of leishmaniasis progression." (PMID 33953862, 2021). "Interestingly, IL-12-mediated DC instruction is confined to IL-4 in leishmaniasis so far, as IL-4 treatment, but not IL-13, enhanced DC-derived IL-12 production." (PMID 33415318, 2020). "Dendritic cell instruction may not be restricted to Leishmaniasis, since other disease models have also demonstrated a protective role for IL-4." (PMID 24204259, 2013).
inflammatory bowel disease (45 papers, 2010 to 2025). A spectrum of small and large bowel inflammatory diseases of unknown etiology. "SNPs in interleukin IL-12β is associated with susceptibility to inflammatory bowel diseases, and SNPs in anti-inflammatory IL-4/IL-4R is associated with susceptibility to type I diabetes mellitus." (PMID 36553455, 2022). "Early reports showed that defect in IL-4 expression in the colonic mucosa was closely associated with patients suffered from inflammatory bowel disease (IBD) and the risk of CRC." (PMID 27121311, 2016). "The interleukin-4 associated single nucleotide polymorphism (SNP) rs2243250 has been associated with development of CDI in Inflammatory Bowel Disease (IBD) patients." (PMID 32796569, 2020). "The previous study has shown that the disrupted IL-2 gene contributes to developing an inflammatory bowel disease similar to UC in humans and IL-2 and IL-4 were defined as anti-inflammatory cytokines which are negatively associated with the occurrence of UC." (PMID 37205093, 2023). "Because of the innate and adaptive features of these cells, and the ability to produce high levels of IL-4 and IFNγ, a role for iNKT cells has been suggested in inflammatory bowel disease and in CD." (PMID 26529008, 2015). "Studies in inflammatory bowel disease demonstrated an impaired IL-4 mediated down-regulation of IL-1b, TNF alpha, and therefore leading to uncontrolled pro-inflammatory cytokine release." (PMID 23472217, 2013). "Future work will utilize these plasmids to test the effects of IL-4 and IL-10 in other chronic murine inflammatory bowel disease models." (PMID 24314293, 2013). "IL-4 plays a critical role in the regulation of immune responses and the pathogenesis of inflammatory bowel disease." (PMID 21172007, 2010). "IL-4 SNPs have been extensively investigated in relation to allergic responses, rheumatic disorders, and cancer, but limited research has been conducted in inflammatory bowel disease patients." (PMID 37189566, 2023). "IL-4 also affects various diseases, particularly inflammatory bowel disease (IBD), where it contributes to chronic inflammation and fibrosis by promoting tissue remodeling and scarring, as well as autoimmune diseases." (PMID 40236667, 2024). "For example, basophilia that is independent of MCs has been associated with inflammatory bowel diseases, but in the context of myocardial infarction, basophils have been associated with tissue repair by increasing IL-4 and IL-13 levels, and altering local monocyte/macrophage responses." (PMID 38780542, 2024). "All of these conditions can be comorbidities in human inflammatory bowel disease (IBD), the target condition for M(IL4) treatment." (PMID 34691050, 2021). "In sum, our studies indicated that commensal microbe-derived butyrate enhanced the IL-4-mediated STAT6 transcription, achieved through H3K9 acetylation to enhance M2-BMDMs polarization, and delineated new insights into the immune interplay underlying inflammatory bowel disease." (PMID 27094081, 2016). "The inflammatory bowel disease is highlighted (q-value = 0.015) through KEGG enrichment analysis using FABIO significant genes, and the involved genes are IL18RAP, IL4, GATA3, and SMAD3 (FABIO PIP = 1, 0.76, 1, and 0.75, respectively)." (PMID 39621803, 2024). "On the other hand, C. versicolor extract showed anti-inflammatory effects in mice model inflammatory bowel disease by reducing STAT1 and STAT6 expression, leading to lower IFN-γ and interleukin-4 (IL-4) expression." (PMID 36676192, 2023). "Multiple cytokines have been studied for their role in the propagation of the inflammatory process related to inflammatory bowel diseases (IBD), but the role of interleukin-4 remains controversial." (PMID 37189566, 2023). "It was also reported that IL-4 and IRS2 play a critical role in the regulation of immune responses and the pathogenesis of inflammatory bowel diseases." (PMID 25144185, 2014).
inflammatory bowel disease (continued). "Seven genes IL10, IL4, IL6, IFNG, IL1B, TNF and IL17A, were engaged in Inflammatory bowel disease." (PMID 36989283, 2023). "In contrast, initiation of IL-4 transcription in naïve T cells is regulated by GATA3; and the expression of GATA3 is significantly increased in the bowel mucosae of children with the inflammatory bowel disease, ulcerative colitis." (PMID 28498822, 2017). "L. lactis (pXIES:CYT:15lox-1)-fermented milk was effective in the prevention of intestinal damage associated with inflammatory bowel disease (IBD) in a trinitrobenzenesulfonic acid-induced IBD mouse model and, in addition, a decrease in IFN-γ and IL-4 was also observed." (PMID 30154762, 2018). "The antiinflammatory activity of CVE in Inflammatory Bowel Disease (IBD) might be mediated by the inhibition of signal transducer and activator of transcription (STAT) STAT 1 and STAT 6 in response to IFN-γ and IL-4 expression." (PMID 28178285, 2017). "Analysis of the other models of disease, that represent comorbidities that can occur in human inflammatory bowel disease (IBD), revealed that M(IL4) treatment did not exaggerate the severity of any of the conditions." (PMID 34691050, 2021). "Unlike inflammatory bowel diseases, there is lack of clear TH1 or TH2 skewing in ASD with the observation that IL-4, IL-2, and interferon gamma (IFN-γ) are elevated in the duodenal mucosa while IL-4 is elevated in the colon." (PMID 29868601, 2018).